INS (insulin)
Diseases named in the same sentence as INS in open-access papers (continued):
Sharing a sentence is not in itself a finding about the gene and the disease.
Obesity (continued). "Results from animal models of obesity showed that treatment with Akkermansia muciniphila reduced insulin sensitivity, fat deposition, and weight gain." (PMID 36674680, 2023). "Surprisingly, TA mice showed resistance to diet-induced obesity, improved insulin sensitivity, and lower fasting lipidemia than their WT and TD counterparts." (PMID 36329235, 2023). "Metabolic changes in normal pregnancy are, in some areas, similar to those of obesity, including reduced insulin sensitivity in late pregnancy." (PMID 36830715, 2023). "Accordingly, PDK1 inhibits FoxO1 to regulate macrophage infiltration, and the PDK1/FoxO1 pathway in macrophages is essential for regulating macrophage polarization and insulin sensitivity in obesity." (PMID 37153549, 2023). "By improving the insulin signaling cascade of the cells, melatonin treatment in animals has been found to reduce obesity and attenuate insulin resistance of the liver and skeletal muscle." (PMID 37441501, 2023). "Computational analyses using Ingenuity Pathway Analysis (IPA) identified multiple activated signaling networks in obesity progression from insulin-resistant and normal glucose-tolerant (IR-NGT) individuals to those with T2D." (PMID 37047308, 2023). "IL-6 suppresses the synthesis of adiponectin and impairs insulin signaling, which together contribute to inflammation in obesity." (PMID 37251328, 2023). "Obesity and overweight conditions dramatically affect systemic energy homeostasis by impacting lipid and glucose metabolism, insulin sensitivity, inflammation, and gut microbiota." (PMID 36674862, 2023). "Strong evidence confirming that chronic inflammation and sex hormone metabolism mediate obesity and cancer is available, with moderate evidence supporting the role of insulin and IGF signaling." (PMID 36860687, 2023). "In this review, all components of this vicious cycle are characterized with particular emphasis on the interplay between insulin signaling and both the innate and adaptive immune responses related to obesity." (PMID 37372966, 2023). "Chemerin release and expression of its receptor CMKLR1 are both increased in obesity and insulin-resistant states and expression of each decreases following weight loss." (PMID 37367914, 2023). "It is important to note that the disturbed regulation of insulin in the central nervous system has been connected to obesity and poor ovarian follicular maturation, which points toward more links between obesity, PCOS, and hyperinsulinemia in animals." (PMID 38021970, 2023). "Conversely, a subgroup of obese individuals (metabolic healthy obesity—MHO) is free of the cardiometabolic risk factors and maintain normal insulin sensitivity, emphasizing the central role of adipose tissue distribution and function in metabolic health." (PMID 37668709, 2023). "BMSC‐Exo treatment of obese mice promoted their metabolic homeostasis, including reduction of obesity, inhibition of M1‐type proinflammatory factor expression, and improvement of insulin sensitivity." (PMID 37073893, 2023). "Leptin and adiponectin, the primary adipokines from adipocytes, are known to impact obesity and insulin sensitivity on a systemic level." (PMID 37513964, 2023). "Overall, these studies highlight the significance of the ECM-integrin-ILK signalling in regulating hepatic insulin action and steatosis in obesity." (PMID 37383542, 2023). "Deletion of PTP1B globally in mice produced a lean phenotype that was hypersensitive to insulin and resistant to diet-induced and/or age-induced obesity, as well as against insulin resistance from chronic inflammation in white adipose tissue." (PMID 37828508, 2023). "The ability of IP6 to modulate digestive hormones, as well as enzymes in lipogenesis, has implications for adipogenesis, obesity, insulin sensitivity, and rates of hepatic lipogenesis." (PMID 37371552, 2023).
Obesity (continued). "This is particularly relevant, as a very recent study showed that oral butyrate supplementation to children with obesity decreased BMI, waist circumference, insulin, and HOMA-IR." (PMID 36810253, 2023). "In obesity, elevated levels of proinflammatory mediators impair insulin signaling in liver, muscle, and adipose tissue cells and cause β-cell dysfunction as well as diminish insulin secretion." (PMID 38026205, 2023). "Overall, the OMVs exerted potential preventive effects on obesity and T2D by decreasing body weight, blood glucose, and increasing plasma insulin." (PMID 37649633, 2023). "Such biologic responses include gluconeogenesis in hepatocytes, adaptive increases in β‐cell insulin secretion in response to obesity and lipid excess, as well as survival of FAO‐dependent cancer cells such as OxPhos‐DLBCLs." (PMID 36917141, 2023). "High-fat diet-induced obesity leads to higher fatty acid synthesis with intramyocellular lipid build up and reduced insulin sensitivity." (PMID 38137341, 2023). "Altered insulin secretion dynamics in response to glucose along an OGTT effectively identifies children with obesity suffering OS and inflammasome activation, despite similar basal glucose, insulin and lipid profiles as well as classical inflammatory markers." (PMID 37599368, 2023). "Thylakoids has anti-obesity activities, stimulating insulin sensitivity and improving the lipid profile through delayed glucose and lipid absorption respectively." (PMID 37576981, 2023). "Many researchers have already validated the pharmaceutical effects of CUR on obesity and glucose/insulin homeostasis through in vitro and in vivo studies." (PMID 37371895, 2023). "Factors associated with poor glycemic control were obesity, DM duration between 5 and 10 years or more than 10 years, retinopathy, and the use of a combination of OHA plus insulin or insulin alone." (PMID 37008178, 2023). "The crosstalk between obesity, T2D, and breast cancer is intricate and mediated by multiple mechanisms including, inflammation, adipose tissue dysfunction, metabolic alterations, insulin, and hypoxia." (PMID 37800138, 2023). "Our results demonstrate TRPM7 as a factor in the development of adipose inflammation that regulates insulin sensitivity in obesity." (PMID 36717580, 2023). "In fact, Boden and colleagues conducted a study enrolling patients with T2DM and obesity, demonstrating that the application of KD for 2 weeks induced the reduction of fasting glycaemia from 7.5 to 6.3 mmol/l and the increase of insulin sensitivity by 75%." (PMID 37405618, 2023). "Conversely, AMPK inactivation in response to leptin and insulin suppresses appetite, preventing obesity and T2DM." (PMID 37303813, 2023). "It is also of practical importance to know that obesity plays a role in reprofiling the type of miRNA released into the circulation, thus influencing insulin resistance, inflammatory processes, and the tumor microenvironment." (PMID 37374323, 2023). "Given the associations between faster post‐natal growth and greater obesity risk in childhood, it is essential to investigate the growth trajectories of metformin‐exposed children to determine whether they differ from those of insulin‐exposed children, according to growth period." (PMID 37597238, 2023). "In contrast, obesity and its accompanying diseases reduce the secretion of adiponectin, an adipokine with insulin-sensitizing and anti-inflammatory properties." (PMID 37055787, 2023). "Consumption of a mixed macronutrient meal and administration of CBD did not influence the glucose response to food in comparison to placebo; however, CBD evoked lower insulin concentrations in males with overweight and obesity compared to placebo." (PMID 37510734, 2023). "In situations like obesity and T2D, FAs coming from both lipolysis and food intake are in excess and eventually accumulate in insulin tissues (liver, skeletal muscles)." (PMID 37178918, 2023).
Obesity (continued). "When compared to similarly obese controls, PHP1a patients had lower insulin sensitivity, indicating that factors other than obesity contribute to lower insulin sensitivity in these patients." (PMID 36773188, 2023). "Studies have found that Bacteroides can lower cholesterol levels, prevent obesity, and improve insulin sensitivity." (PMID 37240315, 2023). "Similar results have recently been reported in children with obesity, with lower insulin sensitivity and worse metabolic profiles being observed among subjects with delayed insulin secretion in response to an OGTT." (PMID 37242230, 2023). "The GNUR treatments also significantly lowered fasting blood glucose and insulin levels in our model of dietary-induced obesity." (PMID 36830621, 2023). "Recent work has ascribed contributory roles for multiple immune cell types, such as monocytes/macrophages, neutrophils, T cells, B cells, dendritic cells, and mast cells, in disturbances in glucose and insulin homeostasis in obesity." (PMID 38048365, 2023). "The BAIBA enantiomer (GABA isomer) recently has been re-discovered as protective myokine, regulating adipose tissue browning, it enhances sensitivity to insulin, and improves obesity induced by a high-fat diet." (PMID 37049464, 2023). "Evidence suggests that both KITLG and insulin can activate PI3K signaling in the context of obesity." (PMID 37432488, 2023). "In obesity, adipose tissue becomes inflamed and dysfunctional, exhibiting a modified biochemical signature and adipokine secretion pattern that promotes insulin resistance in peripheral tissues." (PMID 37761000, 2023). "The relationship between insulin, insulin resistance and blood pressure is quite well known in patients with obesity [69, 70•]." (PMID 37071287, 2023). "This process holds promise in enhancing oxygen consumption and insulin sensitivity, thereby improving obesity and vascular function." (PMID 37919772, 2023). "The impact of obesity on circulating S1P levels and its relationship with markers of glucose metabolism and insulin sensitivity were also investigated." (PMID 37762318, 2023). "Medium chain length SFA reduces fat deposition, which subsequently prevents obesity and increases insulin sensitivity." (PMID 36833442, 2023). "These include the activation of Akt/mTOR signalling pathway by insulin, which is elevated in patients with obesity-induced insulin resistance." (PMID 37173907, 2023). "We found that poor sleep pattern was associated with disrupted insulin homeostasis (elevated FBG) and obesity (elevated WC and BMI); this result is consistent with evidence from previous studies." (PMID 37033270, 2023). "Pharmacological treatments, which include anti-obesity drugs, insulin-sensitizing agents, and insulin-secretagogue medications, have offered solutions to address these illnesses." (PMID 38068738, 2023). "This was also accompanied by a significant increase in insulin sensitivity in the HFD+VNS rats, improving the metabolic syndrome associated with obesity, which has previously been documented." (PMID 38137476, 2023). "Elevated aldosterone and insulin both increase glucocorticoid kinase-1 (SGK-1) activity, which promotes hypertension, IR, and obesity, increasing the risk of CVD." (PMID 38075069, 2023). "Twelve weeks of ILI improved HSI and decreased total daily insulin requirements in patients with T1D and obesity at one year." (PMID 37046323, 2023). "In a context of obesity-induced gut barrier permeability, bEVs and other microbiota-derived products can enter host circulation and reach insulin-sensitive tissues, evidencing the potential of bEVs as biomarkers for intestinal permeability." (PMID 36768391, 2023). "Obesity and its chronic calory excess lead to abnormal levels of glycemia, insulin, cytokines, adipokines and steroid hormones." (PMID 36980693, 2023).
Obesity (continued). "The mechanisms of ceramide action in obesity and metabolic disorders are inhibition of insulin signaling, reduction of fat thermogenesis and browning, and inflammatory response." (PMID 38020719, 2023). "One potential link between the GH–IGF-1 axis and obesity is the molecules’ effects on insulin sensitivity." (PMID 37298507, 2023). "Other factors that negatively affected VAS scores were being female, obesity, insulin usage, and lower levels of education." (PMID 37033039, 2023). "The AdEV cargo from DIO mice should therefore reflect obesity-driven perturbations in lipid metabolism and insulin sensitivity reported for WAT16." (PMID 36759608, 2023). "In OVX- and HFD-induced obese mice, loganin attenuated the representative obesity phenotypes, including hepatic steatosis, adipocyte hypertrophy, and increased plasma levels of leptin and insulin." (PMID 36902181, 2023). "The knockout of SAR1 enhanced insulin sensitivity, improved glucose tolerance, and suppressed obesity in mice." (PMID 37108143, 2023). "Many studies have shown that unsaturated fatty acids can regulate the expression of inflammation-related proteins and NF-kB, reduce inflammation, improve insulin sensitivity, reduce hunger, and improve obesity." (PMID 37063280, 2023). "Despite potential benefits of ketone bodies in neurodegenerative disease, prolonged exposure to them in the hypothalamus can further dysregulate insulin secretion and energy homeostasis, leading to hyperphagia and obesity." (PMID 36984824, 2023). "In mice, Fgf21 administration/overexpression is protective, preventing obesity in animals with diet-induced obesity, and improving hepatic triglyceride concentrations, cholesterol levels, energy expenditure and insulin sensitivity." (PMID 36923222, 2023). "The pathophysiology of NAFLD in obesity is intricate and involves the interaction and dysregulation of several mechanisms, such as insulin resistance, cytokine signaling, and alteration of the gut microbiota." (PMID 37299398, 2023). "Research indicates that visceral fat from ovary-intact females is more insulin sensitive than that from obesity-matched males, as determined by increased protein levels of phosphorylated Akt and ERK in response to insulin stimulation." (PMID 36678314, 2023). "Established metabolomics markers of obesity and insulin sensitivity showed strong correlations with the volume of specific fat depots, waist:hip ratio, and glucose and insulin postprandial curves." (PMID 37661105, 2023). "The main results obtained agree with the results established in the literature for the MSG-obesity model; however, significant alterations in the inflammatory and insulin profile were identified, early in the installation of obesity parameters." (PMID 36902158, 2023). "The high prevalence of obesity, together with its accompanying diseases, has led to increased interest in research on improving insulin sensitivity and inhibiting adipogenesis." (PMID 37529167, 2023). "In youths with obesity, the gut hormone potentiation of insulin secretion — the incretin effect — is blunted." (PMID 37847560, 2023). "Conversely, high-fat-fed mice inhibited adipogenesis due to overexpression of Nrg-4, thereby preventing high-fat diet-induced obesity and fatty liver, and improving insulin sensitivity." (PMID 36915073, 2023). "Some hormones (e.g., leptin, insulin, adiponectin, and ghrelin) are involved in the etiopathogenesis of obesity." (PMID 37513229, 2023). "The CRP levels have been demonstrated to correlate positively with obesity, blood pressure, the triglyceride levels, fasting blood glucose, and insulin sensitivity." (PMID 36674022, 2023). "A mediation analysis found obesity as an important factor modulating fasting glucose and insulin even in children and adolescents with normal weight." (PMID 36980074, 2023). "Murine β-cells also functionally adapt to insulin resistance resulting from high-fat diet-induced obesity." (PMID 37134142, 2023).
Obesity (continued). "Obesity can induce modifications in the structure and function of blood vessels, promote insulin resistance and inflammation, and result in increased sodium retention, thereby posing challenges to achieving effective blood pressure control." (PMID 37416924, 2023). "RIP-Cre is expressed in the brain, including in hypothalamic neurons, and RIP-Cre25Mgn deletion of Lepr results in obesity, impaired glucose-stimulated insulin secretion, and a seemingly paradoxical reduced fasting blood glucose." (PMID 37850099, 2023). "In contrast, it will be interesting to examine to what extent T cells, which only upregulate InsR upon activation, can become insulin resistant, and the metabolic and immune signals that promote IR in T cells during infection and obesity." (PMID 36992811, 2023). "The molecular mechanisms by which obesity affects T2D development include lipid metabolism, insulin sensitivity, and inflammation." (PMID 36837846, 2023). "In several models, DNA damage was shown to be enhanced by estrogen and insulin signaling; two hormones that likely mediate many adverse effects of obesity on breast cancer." (PMID 37800138, 2023). "The presence of overweight/obesity was also associated with lower adherence to diet, increased use of metformin, family history of obesity in first-degree relatives, use of higher total daily insulin dose, and type of health care insurance." (PMID 36823646, 2023). "The phenotype is characterized by decreased fat deposition, lower plasma concentrations of glucose, insulin and cholesterol, higher glucose tolerance and insulin sensitivity, and resistance to diet-induced obesity." (PMID 37267233, 2023). "Although insulin has long been thought to be a critical mediator of obesity-driven cancer, in vivo evidence for a role in early tumor development in faithful cancer models has only recently emerged." (PMID 37648285, 2023). "These pathological conditions (dysbiosis, inflammation, insulin resistance, adipocytokine deregulation) are common in severe obesity." (PMID 37029427, 2023). "In contrast, the carbohydrate insulin model (CIM) suggests that obesity is specifically exacerbated by excessive consumption of refined carbohydrates, especially caloric sugars." (PMID 37479702, 2023). "Th17 cells characterize a subclass of CD4+ T cells that can produce interleukin-17 (IL-17), which plays a role on body weight control, adipocyte differentiation, insulin and glucose homeostasis, and low-grade sustained inflammation related to obesity." (PMID 36845826, 2023). "Most obesity-related genes are involved in appetite-related signals, adipocyte growth and differentiation, energy expenditure regulation, or insulin metabolism and adipose tissue inflammation." (PMID 37511320, 2023). "By contrast, in an animal experiment, AIM2-/- mice were more prone to obesity, impaired brown fat function, increased fasting blood glucose and insulin levels, and impaired metabolic functions such as IR when compared to WT mice." (PMID 36993972, 2023). "In contrast, the expression of PHLPP1, which hampers the insulin signaling cascade, was reduced in the obesity mice models compared to shSCR-infected mice." (PMID 36866247, 2023). "Nonetheless, ad libitum–fed blood glucose and plasma insulin levels were still reduced in transgenic mice, indicating sustained insulin sensitivity upon diet-induced obesity." (PMID 37150323, 2023). "Through upstream pathways shared by IKKβ/NF-κB in response to stress signals including fatty acids (FAs), insulin, hyperglycemia, and inflammatory cytokines, obesity also activates JNK in insulin-responsive tissues." (PMID 37346355, 2023). "GPR21 knockout mice are resistant to diet‐induced obesity with higher glucose metabolism and insulin sensitivity." (PMID 36721851, 2023). "Adipocyte-specific elimination of TRPM7 maintains insulin sensitivity and protects mice from diet-induced obesity and adipose inflammation." (PMID 36717580, 2023).